TFF2 (trefoil factor 2)
Diseases named in the same sentence as TFF2 in open-access papers (continued):
Sharing a sentence is not in itself a finding about the gene and the disease.
tumor (40 papers, 2007 to 2025). "Tff2 inhibition likely promotes tumor growth due to the loss of anti-proliferative gastrokine and Tff1 genes." (PMID 32231118, 2020). "The transfer of MDSCs from Tff2-null mice resulted in a marked (10-fold) stimulation of tumour growth in CD2–Tff2 mice, converting the tumour-resistant CD2–Tff2 mice into a tumour susceptible phenotype." (PMID 26841680, 2016). "Analysis of the correlation between TFF2 expression and clinicopathological data showed that decreased TFF2 expression was closely associated with tumor cell differentiation and lymph node invasion." (PMID 24765170, 2014). "The complex gene expression profile of all-low tumor (ALDH6A1 + TFF2 + MCM5) was strongly associated with ORR in the Bevacizumab qPCR set (ORR 85.7%, p = 0.007), but not in the Control set (ORR 36.4%, p = 0.747)." (PMID 24555920, 2014). "Importantly, ROC analysis further confirmed that TFF2 achieved superior diagnostic accuracy for PC, surpassing conventional tumor markers with higher AUC values." (PMID 41040532, 2025). "Furthermore, we evaluated the diagnostic potential of TFF2 in comparison with conventional tumor markers at the mRNA level through ROC curve analysis." (PMID 41040532, 2025). "In addition, we found out that the proliferative ability was suppressed followed by the mutation of TFF1-MS and TFF2-MS in tumor cells." (PMID 36428568, 2022). "Overexpression of TFF2 led to a slight increase in tumour-associated dendritic cells, which might also contribute to tumour immunity." (PMID 26841680, 2016). "Finally, the profile of all-low (ALDH6A1 + TFF2) tumor gene expression showed a marginally significant association with superior survival in the chemotherapy-only Control set, but not in the Bevacizumab qPCR set." (PMID 24555920, 2014). "Furthermore, H. pylori infection can cause methylations on CpG islands of E-cadherin and tumor-suppressor genes, including those encoding the trefoil factor 2 (TFF2) and a forkhead box transcriptional regulator (FOXD3), resulting in the significantly increased risk of adenocarcinoma in the stomach." (PMID 29474889, 2018). "The AUC value of the model consisting of the four genes (CHI3L1, FCGBP, VSIG2, and TFF2) outperformed other tumor markers and performed well in predicting the prognosis of GC patients." (PMID 40084401, 2025). "The M17 gene module comprises core genes including TIMP1, TFF2, ITM2A, SPINK1, and TSPAN8, intimately associated with tumor stemness maintenance and invasion-metastasis capacity." (PMID 41450464, 2025). "The results revealed that TFF2 was predominantly secreted by epithelial cells and exhibited elevated expression in tumor samples, highlighting its potential of TFF2 as a blood biomarker for PC." (PMID 41040532, 2025). "In contrast, C1 and C3 exhibited overexpression of trefoil factor family genes (TFF1, TFF2, and TFF3), which are associated with angiogenesis, apoptosis, and tumour progression." (PMID 37994257, 2024). "Based on the survival analysis, the TFF1/TFF2 high-expressed cohort presented favorable overall survival (OS) and tumor-free survival (TFS) as compared to the TFF1/TFF2 low-expressed cohort." (PMID 36428568, 2022). "Through the integrative analysis, it was observed that TFF1 and TFF2 were low expressed in tumor specimens, and their mRNA expressions were negatively associated with the DNA methylation level." (PMID 36428568, 2022). "The lower expression levels of TFF1 and TFF2 were observed in GC tumor tissues as compared to those in normal tissues." (PMID 36428568, 2022). "The second ranked module, M434, represents downregulation of tumor suppressors such as TFF2, GKN1 and GKN2 in gastric mucosal barrier (GMB) homeostasis in GC." (PMID 31463974, 2020). "Therefore, loss of Tff1 or Tff2 expression (TFFs peptides) could lead to tumor growth." (PMID 32231118, 2020).
tumor (continued). "Our study extended our understanding of the role of splenic TFF2 inhibition-mediated MDSCs expansion in the spleen in postoperative immunosuppression, not only in tumor-mediated immunosuppression." (PMID 32200357, 2020). "TFF1 is a well-known gastric-related tumor suppressor gene, whereas the function of TFF2 in GC is relatively less investigated." (PMID 32122390, 2020). "One previous study indicates that the increase in the spleen weight is accompanied by an increased expansion of MDSCs in the spleen due to the decreased expression of splenic TFF2 after tumor-mediated immunosuppression." (PMID 32200357, 2020). "Similar, after modification of the C-terminus with CTP, TFF2 still retained the ability to decrease tumor growth via suppression of myeloid cells in vivo." (PMID 30042499, 2019). "TFF2 expression was detected in BxPC-3, AsPc-1, Capan-1, CFPAC, HPac, Capan-1, SNU-213, Capan-2, Panc 03.27, and Panc 02.13, implying that TFF2 selected from genome-wide expression profiles is mainly expressed by tumor cells in the utilized tissue specimens." (PMID 30533259, 2018). "Unfortunately, we were unable to find a correlation between TFF2 expression levels and cancer cell lines of different stages, as many of these tumor cell lines are of an uncertain origin and stage." (PMID 30533259, 2018). "Depletion of CD8+ T cells in CD2–Tff2 mice treated with AOM/DSS resulted in a marked (10-fold) increase of tumour growth, indicating that the protective effect of Tff2 overexpression depended on CD8+ T-cell immunity." (PMID 26841680, 2016). "More importantly, following the AOM–DSS protocol, recipients of Tff2-null bone marrow as expected developed the greatest tumour burden (n=3 per group)." (PMID 26841680, 2016). "In contrast, the Tff2-null mice had the most MDSCs and exhibited the greatest number of tumours, which showed a higher dysplasia grade and a greater area of dysplasia by both histology and nuclear β-catenin immunostaining." (PMID 26841680, 2016). "To prove that CD11b+Gr-1+ cells directly contributed to tumour progression, we performed adoptive transfer of MDSC sorted from spleen and bone marrow of tumour-bearing Tff2-null mice into AOM/DSS-treated CD2–Tff2 mice." (PMID 26841680, 2016). "In the qPCR and IHC analyses of the current study, the decreased expression of TFF2 was 92.9% and 81.8%, respectively, and the reduced expression was found to significantly correlate with tumor cell differentiation and invasion." (PMID 24765170, 2014). "The Odds Ratio for response for the all-low tumor (ALDH6A1 + TFF2 + MCM5) profile versus any other ALDH6A1 + TFF2 + MCM5 profile was 15 (p = 0.018) in the Bevacizumab qPCR set but only 0.72 (p = 0.63) in the Control set." (PMID 24555920, 2014). "Multiple tumor suppressors were expressed at lower levels in EBVaGCs including five (TFF2, RBP4, HOXA9, LRRN1, and RAP1GAP) that are known to be hypermethylated in cancers." (PMID 23671415, 2013). "The non-functional TFF2 cannot mediate cell proliferation like its canonical TFF2 preventing tumor cell progression." (PMID 22159958, 2012). "TFF2 achieved an AUC of 0.904 in diagnosing PC, significantly outperforming other tumor markers." (PMID 41040532, 2025). "In addition, the downregulation DNMT1 induced the low DNA methylation level of cg2406316 of TFF2 in tumor cells." (PMID 36428568, 2022). "H. pylori infection can induce methylations on E-cadherin CpG islands and tumor-suppressor genes, consisting of those which encode a forkhead box transcriptional regulator (FOXD3) and the trefoil factor 2 (TFF2), which markedly increase the adenocarcinoma risk in the stomach." (PMID 34556055, 2021). "SVN is important for splenic TFF2 expression in tumor-mediated immunosuppression." (PMID 32200357, 2020). "SVN also exerts key roles in promoting splenic TFF2 expression in tumor-mediated immunosuppression." (PMID 32200357, 2020).
tumor (continued). "While TFF2 induced the migration of immature DCs in a dose-dependent manner, LPS-stimulated DCs exhibited poor migratory activity in response to TFF2, implying that TFF2 secreted by tumor cells is a chemoattractant for immature DCs, preventing their migration to lymph nodes from tumors." (PMID 30533259, 2018). "This was due to a reduction in MDSCs, since tumour suppression could be overcome by adoptive transfer of MDSCs from TFF2-null mice, and abrogated by immune depletion of CD8+ T cells." (PMID 26841680, 2016). "Both wild-type and Tff2-null mice injected with Ad-Tff2 had fewer peripheral MDSCs in blood and spleen, and developed significantly fewer tumours versus control." (PMID 26841680, 2016). "Some of these are: CDH1 that codes for E-cadherin, a transmembrane glycoprotein involved in maintaining epithelial integrity; GATA4 and GATA5 encoding transcription factors; and TFF2 (encoding trefoil factor 2) and FOXD3 (encoding a forkhead box transcriptional regulator) that are tumor suppressors." (PMID 24723914, 2014). "TFF2 has been suggested as a tumor suppressor in gastric carcinogenesis and metastasis." (PMID 24765170, 2014). "It has been shown that TFF2 is involved in tumor progression in CCA." (PMID 22159958, 2012). "These genes are involved in the regulation of immune/inflammatory response (Lgals1, Ptgds, Tff2, Ubd), tumor angiogenesis (Lgals1, Esm1, Ndrg1), epidermal growth factor signaling (Erbb4, Nrg1), response to tissue injury (Tff2, Vnn1), and gene transcription (Id3, Ifrd1)." (PMID 19340302, 2009). "Furthermore, a number of interferon (IFN) response genes (BST2, CD74, HLA-DMA, HLA-DPB1, HLA-DQB1, HLA-DRA, HLA-DRB1, and IRF8) were upregulated in C10 compared to the other clusters, whereas genes associated with tumor suppression and apoptosis (TFF1 and TFF2) were downregulated." (PMID 37370788, 2023). "Furthermore, TFF2 expression significantly increased in L22P mice versus WT (p < 0.001), suggesting that gastric mucous cells likely display precancerous stage of tumor initiation." (PMID 31216714, 2019). "However, we observed marked differences in tumour development in mice that received wild-type versus TFF2-null versus CD2–Tff2 bone marrow transplants, thus indicating the predominant role of hematopoietic, rather than epithelial, TFF2 expression at least for colorectal carcinogenesis." (PMID 26841680, 2016). "Therefore, there was reduced TFF2 expression in poorly differentiated tumor cells compared with well- and moderately differentiated tumor cells, and reduced TFF2 expression in positive lymph node invasion tumors compared with negative lymph node invasion tumors." (PMID 24765170, 2014). "Finally, we assessed the diagnostic performance of TFF2 alongside conventional tumor markers, including CEA (CEACAM5) and CA125 (MUC16), for PanIN and PC through ROC curve analysis, and the AUC values were 1.000 and 0.904, significantly outperforming other tumor markers." (PMID 41040532, 2025). "Analyzing a cohort of 100 tumor samples and 62 normal samples, including datasets GSE15471, GSE16515, and GSE32676, a significant upregulation of TFF2 was observed in PC samples compared to normal control (P<0.05, P<0.001)." (PMID 41040532, 2025). "(C) Violin plots of single-cell sequencing data showing expression levels of Gkn1, Tff1, Tff2, Cym, Pgc, Pga5, and Pou2f3 transcripts in BPN tumor clusters 1–3 and highlighting key drug-mediated cell-identity changes." (PMID 33821796, 2021). "M434 captures a tumor suppressive axis TFF1‐TFF2‐GKN1‐GKN2, where TFF2, GKN1/2 are found in M434, and TFF1 is found at a neighboring module directly connected to M434." (PMID 31463974, 2020). "Splenic TFF2 plays key roles in inhibiting MDSCs expansion in the spleen and thus increasing CD8+ T cells activity in tumor-mediated immunosuppression." (PMID 32200357, 2020).
tumor (continued). "Tumor tissue samples from patients with unfavorable PFS status were found to overexpress four out of the five genes (AGR2, ALDH6A1, TFF2, MCM5) and underexpress KLF12." (PMID 24555920, 2014). "Our recent study reported that TFF2 positive immunostaining was markedly increased in CCA compared with those in normal bile ducts and dysplasia suggesting the role of TFF2 in tumor progression." (PMID 22159958, 2012). "Three molecules, TFF2 (trefoil factor 2), PSCA (prostate stem cell antigen), and NGAL, were scored very highly in tumours compared to the normal pancreas." (PMID 18392050, 2008). "The five independent prognostic genes were mainly expressed in cancer stem cells and epithelial cells, in particular, SLC2A1 and TFF2 were significantly high-expressed in epithelial cells in the tumor group than in nontumor group." (PMID 40662145, 2025). "Focusing on CRC patients with high tumor purity from the TCGA database, we found a resistant oncogenic signature of immune evasion (including REG4, CTSE, MUC1, TFF2, LCN2) that inversely correlated with cytotoxicity and immune infiltration deconvolution scores (T- and NK-cells)." (PMID 39632825, 2024). "Moreover, tumor clusters had higher expression levels of tumor makers, including LAMC2, MSLN, TFF2, and CEACAM5, compared with ductal clusters, which further verified their tumor identity." (PMID 36944944, 2023). "Both MUC1 and TFF2 expression showed a slight decreased in cardia tissue compared with non-cardia tumor tissue, but there were no significantly differences." (PMID 32122390, 2020). "Additional staining of full-blown tumors for markers expressed in normal antral glands revealed that GLI2A-expressing tumor cells did not express Muc5ac or Tff2, and infrequently stained with the mucin-binding lectins GSII and UEA1." (PMID 26859571, 2016). "AOM/DSS-treated wild-type mice receiving splenic IMCs from untreated CD2–Tff2 mice developed a lower number of tumours and a lower proportion of MDSC but a higher proportion of CD8+ cells in the colon compared with wild-type mice that received splenic IMC from Tff2-null mice." (PMID 26841680, 2016). "TFF2 upregulated ApoE but ApoE−/−/CD2–Tff2 mice did not develop significantly more tumours than CD2–Tff2 mice, suggesting some functional redundancy within this system." (PMID 26841680, 2016). "Moreover, TFF2 positive immunostaining in CCA was markedly increased compared with normal and precancerous tissues suggesting its important role in tumor progression." (PMID 22159958, 2012). "In addition, the five independent prognostic genes were mainly expressed in cancer stem cells and epithelial cells, in particular, the expressions of SLC2A1 and TFF2 in epithelial cells of tumor group were notably higher than those of nontumor group." (PMID 40662145, 2025). "According to the result of scRNA-seq analysis, the five prognostic SRRGs were mainly expressed in cancer stem cells and epithelial cells, in particular, the expressions of SLC2A1 and TFF2 in epithelial cells of tumor group were notably higher than nontumor group." (PMID 40662145, 2025). "The suppression of tumour growth in response to TFF2 overexpression in the AOM/DSS model was not, however, significantly altered by knockout of the ApoE gene, suggesting that there may be other important signalling targets beyond ApoE." (PMID 26841680, 2016). "Thus, given the absence of significant colonic TFF2 expression expansion of MDSC and tumour burden were inversely associated with splenic TFF2 status." (PMID 26841680, 2016). "Interestingly, Tff2-knockout mice were particularly susceptible to gastric inflammation and cancer, and TFF2 expression decreased during gastric carcinogenesis because of methylation of the TFF2 gene promoter, suggesting that TFF2 or SPEM may act as a tumor suppressor." (PMID 28953255, 2017).
tumor (continued). "The TFF2 antibody was evaluated in 204/206 TMA hybridized samples (99%; 2 samples [MC sample 110 and HGSC sample 5353] were not assessed due to missing tumor and/or core N/A [not available]) and displayed a more heterogeneous staining pattern." (PMID 36818673, 2022).
cancer (39 papers, 2012 to 2025). A tumor composed of atypical neoplastic, often pleomorphic cells that invade other tissues. "The expression of CD44 variants and TFF2 expansion are key markers of human gastric metaplasia and are associated with cancer stem cell properties and progression risk." (PMID 40673273, 2025). "TFF2 mRNA expression was significantly decreased in cancer tissues compared with the associated normal mucosa." (PMID 24765170, 2014). "Based on these observations, we believe that systemic administration of recombinant TFF2 could provide a substantial therapeutic benefit in the treatment of malignancies, particularly inflammation-associated cancers." (PMID 30042499, 2019). "Together, these data confirm that TFF2 from T cells suppresses the development of splenic MDSCs, which may be a critical step in modulating cancer risk." (PMID 26841680, 2016). "Our findings confirmed that TFF2 could serve as a promising serum biomarker for the early detection of PC, enabling the identification of high-risk individuals before the development of invasive cancer." (PMID 41040532, 2025). "This lineage-tracing data provides direct evidence that TFF2+ isthmus progenitor cells can serve as cells-of-origin for gastric dysplasia, supporting the stem cell theory of cancer development in human gastric carcinogenesis." (PMID 40673273, 2025). "Meanwhile, the TFF2 CpG island site cg26403416 (TFF2 MS) presented higher DNA methylation levels in cancer than normal specimens." (PMID 36428568, 2022). "For instance, this is the case of Trefoil factor 2 (TFF2), a secreted protein of the gastrointestinal mucosa that is up-regulated in many cancer types, including iCCA." (PMID 35008179, 2021). "This vagally mediated circuit can be enhanced by exogenous delivery of TFF2, either through bone marrow transplantation or by an adenoviral vector, both of which suppressed MDSCs and prevented cancers." (PMID 26841680, 2016). "Similar to IL33, TFF2 expression is lost during chronic H pylori infection in human beings, and its expression decreases progressively as cancer advances." (PMID 28210674, 2015). "RT-PCR was performed on matched normal and cancer specimens randomly selected from four patients and the results showed PAR4 and TFF2 mRNA levels significantly increased in cancers tissues when compared to the matched normal tissues." (PMID 25876034, 2015). "In our research, it was interesting to find TFF2 expression was also increased in cancer tissues when compared to the relative normal colorectal mucosa." (PMID 25876034, 2015). "Three closely related trefoil factors (TFFs) known in humans, pS2 (TFF1), spasmolytic polypeptide (SP or TFF2) and intestinal TFF (ITF or TFF3), have been previously reported to be associated with the development of various types of cancer." (PMID 24765170, 2014). "In detail, TFF2 expression was decreased in 86.9% of poorly differentiated cancers and 65.4% of well- and moderately differentiated cancers (P=0.02; χ2 test)." (PMID 24765170, 2014). "In detail, TFF2 was expressed in the neck cells and the deeper glands of the normal gastric mucosa, but the expression was significantly decreased in the cancer tissues." (PMID 24765170, 2014). "A subsequent pan-cancer analysis validated TFF2 as a highly specific marker for PC." (PMID 41040532, 2025). "The results showed that TFF2 expression was significantly elevated in the PC group compared to the benign control, and TFF2 demonstrated the best performance in distinguishing pancreatic benign conditions from malignancies, with an AUC of 0.924." (PMID 41040532, 2025). "Accordingly, TFF2 was selected for subsequent analysis due to its cancer specificity." (PMID 41040532, 2025). "Moreover, the increased expression of CXCR4 in situations in which TFF2 is also overexpressed, such as cancer, further supports such molecular links." (PMID 34944474, 2021).